IL17A (interleukin 17A)
Diseases named in the same sentence as IL17A in open-access papers (continued):
Sharing a sentence is not in itself a finding about the gene and the disease.
COVID-19 (607 papers, 2020 to 2026). A disease caused by infection with severe acute respiratory syndrome coronavirus 2. "Several reports have associated the increased IL-17A levels and Th17 response in the upper and lower respiratory tracts of COVID-19 patients with COVID-19 severity." (PMID 40003732, 2025). "While IL-17A has been implicated in severe COVID-19 cases by fueling inflammation and cytokine storms, our data suggest a different contribution in asymptomatic subjects." (PMID 41357245, 2025). "In COVID-19, the IL-17A is elevated in a few studies and is mainly associated with the severity of COVID-19, a finding corroborated by our study." (PMID 39861879, 2025). "Cytokines like interleukin (IL) IL-10, IL-17A, and IL-1β play pivotal roles in the inflammatory response associated with severe COVID-19." (PMID 39062105, 2024). "The significant roles of INF-g and IL17a, beyond their contributions to COVID-19 mortality and tissue damage, also underline the necessity of understanding the broader immunological landscape." (PMID 39203987, 2024). "Tuberculosis is associated with a decline in Th17 cell level, while COVID-19 immunopathogenesis seems related to elevated levels of IL-17A." (PMID 38004820, 2023). "Still, ORF8′s ability to imitate IL-17A appears to contribute to immune system hyperactivation and cytokine storm associated with poor COVID-19 prognosis." (PMID 37112851, 2023). "IL-17A has been found to be associated with neurological sequelae and pulmonary fibrosis in post-COVID-19 patients." (PMID 37528111, 2023). "Several reports have also associated the increased IL-17A levels and Th17 response in upper and lower respiratory tracts of COVID-19 patients with COVID-19 severity." (PMID 36136963, 2022). "Specifically, we identify lower levels of LPS-stimulated IL-1β, and R848-stimulated IL-12 and IL-17A, at hospital admission to be significantly associated with increasing COVID-19 disease severity during hospitalization." (PMID 36101705, 2022). "This study revealed that the newly identified IL17A/F gene, which is associated with the severity of COVID-19, is a common genetic factor between populations." (PMID 35264675, 2022). "Both mild and severe COVID-19 cases have been associated with higher levels of IL-17A, with the highest levels observed in severe cases." (PMID 36034704, 2022). "rs3819025: The G allele (GG and GA) shows a direct association with higher IL-17A tissue expression in the COVID-19 group than the homozygous A allele." (PMID 33868301, 2021). "Although the study’s focus was COVID-19, our results also indicated an association between rs2275913 and higher IL-17A tissue expression in the H1N1 group." (PMID 33868301, 2021). "High IL-17A and GM-CSF protein levels in the serum of patients with COVID-19 were associated with a more severe clinical course." (PMID 33622974, 2021). "An elevated level of immunomodulatory cytokines, including IL-1α, IL-1β, IFN-α, IL-17A, and IL-12p70, constitute COVID-19 signature that exhibits dynamic features associated with clinical manifestations." (PMID 34912345, 2021). "The inflammatory cytokine profile of Pso patients at risk for COVID-19 included in our study showed increased levels of IL-18, IL-17A and IL-6 and decreased levels of IL-27 when compared to HCs." (PMID 34068473, 2021). "Accordingly, high saliva levels of IL-17A have been associated with COVID-19 severity." (PMID 39493750, 2024). "The role of INF-g, identified as an independent risk factor associated with COVID-19 mortality, and the implications of IL17a in exacerbating immune responses and lung tissue damage are particularly complex but critical in understanding COVID-19’s immunopathology." (PMID 39203987, 2024). "Previous studies showed an association of IL-17A salivary levels with COVID-19 severity, as well as an imbalance in the Th17/Treg axis, leading to the suggestion that an IL-17A blockade could constitute a viable therapeutic strategy." (PMID 39493750, 2024).
COVID-19 (continued). "Our research group has demonstrated that hDPSCs can modulated the production of cytokines such as TNFα, IFNγ, IL-10 and IL-17A by peripheral blood mononuclear cells (PBMCs) obtained from Coronavirus disease 2019 (COVID-19) patients." (PMID 39450172, 2024). "Moreover, high levels of tissue-resident memory-like CD4+ T cells expressing high amounts of the genes encoding the proinflammatory cytokines IL-17A/F and GM-CSF were identified in the lungs of patients with COVID-19 even after clearance of the virus." (PMID 36146622, 2022). "The eQTL data using the Genotype-Tissue Expression (GTEx) database for three SNPs that met the genome-wide significance level in the IL17A/IL17F gene region showed that IL17F mRNA expression levels were significantly reduced by carrying the risk allele associated with COVID-19 severity." (PMID 35264675, 2022). "Another intriguing observation was the association between LPO with IL-7 and IL-17A levels, which may indicate a mechanism by which COVID-19 leads to a cytokine storm and lymphopenia." (PMID 36499671, 2022). "IL-2 and IL-17A were independent risk factors that could lead to liver injury in coronavirus disease 2019 (COVID-19) patients at admission." (PMID 35401547, 2022). "We evaluated IL-17A, TNFα, IL-1β protein levels in saliva of COVID-19 patients with different severities, and found that among these cytokines, IL-17A was associated with COVID-19 severity and poor patient survival outcomes." (PMID 36136963, 2022). "Besides, the GG/GA genotypes of this SNP are associated with a higher tissue expression of IL-17A in the COVID-19 group." (PMID 33868301, 2021). "Indeed, the severity of COVID-19 was associated with increasing systemic levels of IL-17A or Th17-like cells, and its inhibition has been proposed as a potential treatment for this disease." (PMID 33821263, 2021). "Overall, CEC attributes of convalescent COVID-19 patients correlated with a vast majority of differentiation and activation factors associated with T cells and B cells (IL-4, IL-5, IL-7, IL-17A, IL-18, MIP-1α, and RANTES), implicating a broad adaptive immune response with endothelial dysfunction." (PMID 33752798, 2021). "Moreover, elevated IL-17A and GM-CSF protein in the serum of patients with COVID-19 have been associated with a more severe clinical course." (PMID 34064728, 2021). "rs2275913: The genotype GG could be associated with the higher IL-17A tissue expression than GA in the COVID-19 group." (PMID 33868301, 2021). "This study significantly advances our understanding of COVID-19 severity by evaluating a comprehensive panel of cytokines and clinical markers, confirming the robust association between elevated levels of IL-1β, IL-6, IL-8, IL-10, IL-17A, IL-23, TNF-α, and IFN-α with critical disease outcomes." (PMID 39861879, 2025). "Our finding that small subgroups of patients in our cohorts have increased IL-17A or IL-5 in serum, points to additional immunotypes that may have distinct clinical characteristics in acute infection or associate with post-recovery sequelae of long COVID-19." (PMID 35177626, 2022). "Besides, IL17A genotyping demonstrated that the G allele of rs3819025 (G/A) might be considered a risk allele in COVID-19 patients and associated with the highest IL-17A tissue expression." (PMID 33868301, 2021). "Intriguingly, we found a strong positive correlation between the plasma sCD14 levels and IL-17A in both acute COVID-19 and LC patients, respectively." (PMID 41522693, 2026). "Key Th17 effector cytokines, including members of the IL-17 family (primarily IL-17A and IL-22), play crucial roles in the pathogenesis of COVID-19 and periodontitis." (PMID 41463036, 2025). "Elevated IL17A levels have been observed in severe COVID-19, correlating with hyperinflammation and poor prognosis." (PMID 41227320, 2025).
COVID-19 (continued). "Our findings confirm previous studies showing higher expressions of TMPRSS2, ADAM-17, and IL-17A in healthy individuals compared to COVID-19 patients, recovered, and vaccinated individuals." (PMID 40003732, 2025). "The current study aims to investigate the predictive value and diagnostic potential of interleukins IL-10, IL-17A, IL-1β, IL-6, CXCL, and MCP for severe COVID-19 and COVID-19 mortality." (PMID 39062105, 2024). "The newly reported genetic variant of ACE2 showed a positive correlation with CD40L, IL-1β, IL-2, IL-15, and IL-17A in COVID-19 patients." (PMID 38855114, 2024). "As IL-17A is reported to be involved in COVID-19 disease progression, we analyzed the levels of IL-17A in the supernatant of positive samples." (PMID 39066169, 2024). "Th17 cells characterized by high IL-17A and GM-CSF expression are enriched and clonally expanded in the lungs of COVID-19 patients with severe disease, potentially contributing to lung damage through interacting with CD8+ T cells and macrophages." (PMID 39066169, 2024). "Here, we investigated the effect of SARS-CoV-2 infection and COVID-19 vaccination on various T-cell populations and IL-17A levels in maternal blood samples collected throughout gestation in a large, diverse pregnancy cohort in NYC." (PMID 38504979, 2024). "The utility of compound scores, particularly a weighted sum of IL-6, MCP, CXCL, IL-6, IL10, IL-17A, and IL-1β, were particularly stronger in predicting disease severity, reinforcing the potential of a multifaceted biomarker approach in managing COVID-19." (PMID 39062105, 2024). "IL17a, known for its role in promoting inflammation and tissue damage, emerges as a potential key player in the pathogenesis of COVID-19, particularly in severe cases." (PMID 39203987, 2024). "The ELF concentrations of IL-6, IL-8, IL-17A, IL-25, and IL-31 were significantly increased in COVID-19 patients." (PMID 38654351, 2024). "Compared to epithelial cells isolated from 15 healthy controls, epithelial cells isolated from eight individuals with severe COVID-19 expressed significantly higher levels of genes that were also induced by IL17A exposure in vitro." (PMID 38687064, 2024). "Pronounced expression of complement proteins (C1q, C3, C3b, C4, C5) and inflammatory cytokines (TNF, IL-1α, and IL-17A/E) was detected in the fetal compartment of COVID-19-affected pregnancies." (PMID 39390219, 2024). "In other infections such as COVID-19, increased levels of IL-17A, among other pro-inflammatory cytokines, have been associated with very poor prognosis including multiple organ dysfunction and death." (PMID 37525227, 2023). "In the severe COVID-19 group, we observed a hyperinflammatory state, as judged by increased concentration of cytokines (IL-1α, IL-4, IL-6, IL-10 and IL-17A), chemokines (IP-10 and MIP-1β), and adhesion markers (E-selectin and ICAM-1)." (PMID 37441066, 2023). "In addition to high early IFN responses, moderate COVID-19 is associated with increased plasma levels of a core of pro-inflammatory cytokines, chemokines and growth factors (e.g., IL-1a, IL-1β, IFNα, IL-12p70, and IL-17A) that are effectively resolved during infection." (PMID 37491352, 2023). "Along the same lines, patients with long-standing COVID-19 have been reported to have a pro-inflammatory cytokine profile characterized by higher levels of IL-1β, IL-6, IL-13, IL-17A, TNFα, IFNγ-induced protein-10 (IP-10), and G-CSF." (PMID 36836568, 2023). "IL-17A has been suggested as the main cytokine responsible for respiratory distress syndrome in COVID-19 during the cytokine storm." (PMID 37239991, 2023). "As the results show, the number and percentage of PsA patients treated increased in the period of COVID-19, and so did the prescription of IL-17A inhibitors, ixekizumab and others, as the therapy of choice in PsA." (PMID 37623450, 2023).
COVID-19 (continued). "As a pro-inflammatory cytokine, IL-17A signaling has been related to the hyper-inflammatory state and lung inflammation observed in severe COVID-19, with disease severity positively correlating with IL-17A levels." (PMID 37112851, 2023). "Regarding specific treatment with biologic DMARDs, IL-6 receptor inhibitors were prescribed less frequently (lower prescription of tocilizumab), whereas IL-17A inhibitors were prescribed more frequently during COVID-19 (higher prescription of ixekizumab)." (PMID 37623450, 2023). "Using the clonotype information of resident memory cells producing IL-17A in inflamed lung (TRM17), we further corroborated the existence of the newly identified population of IL-17A-producing TH17 cells in reconstructed COVID-19 blood data." (PMID 37730638, 2023). "Convalescent COVID-19 children had elevated levels of IFNγ, IL-2, TNFα, IL-1α, IL-1β, IFNα, IFNβ, IL-6, IL-12, IL-17A, IL-10 and G-CSF in comparison to control children." (PMID 37013538, 2023). "Analysis of cytokine at pretreatment showed that the COVID-19 positive patients had significantly elevated levels of IL-17A, IL-6, IL-10, MIG, MCP-1 and IP-10." (PMID 37662953, 2023). "Although correlations between interleukins are shown in this study, more in-depth studies are necessary for a full understanding of the influence and interaction of IL-17A with other inflammatory cytokines in COVID-19 patients." (PMID 38283346, 2023). "CD4+ T cells from severe COVID-19 patients had decreased expression of IFNγ and IL-17A in relation to cells from patients with the moderate form of the disease or healthy donors." (PMID 37523305, 2023). "At baseline, there were significantly increased frequencies of CD4+ T cells expressing IFN-γ IL-2, TNF-α, and IL-17A in MIS-C compared with children with COVID-19 or with other infectious diseases." (PMID 38116577, 2023). "At baseline, there were significantly increased frequencies of CD8+ T cells expressing IFN-γ, TNF-α, and IL-17A in MIS-C compared to children with COVID-19 and other infectious diseases." (PMID 38116577, 2023). "In response to SARS-CoV-2 S-RBD and SARS-CoV-2 ICL, we observed significantly increased frequencies of CD4+ T cells expressing IFN-γ, IL-2, and IL-17A in MIS-C compared to children with COVID-19 and other infectious diseases." (PMID 38116577, 2023). "Of the analyzed pro-inflammatory cytokines, the concentrations of interleukin (IL)-1β, monocyte chemotactic protein 1 (MCP-1), IL-6, IL-8 and IL-17A were significantly higher in severe COVID-19 patients compared to healthy controls." (PMID 36851312, 2023). "In response to SARS-CoV-2 S-RBD and SARS-CoV-2 ICL, we observed significantly increased frequencies of CD8+ T cells expressing IFN-γ, IL-2, TNF-α, and IL-17A in MIS-C compared to children with COVID-19 and other infectious diseases." (PMID 38116577, 2023). "Convalescent COVID-19 children had elevated levels of IFNγ, IL-2, TNFα, IL-1α, IL-1β, IFNα, IFNβ, IL-6, IL-12, IL-17A and G-CSF in comparison to control children." (PMID 37013538, 2023). "It was shown that the expression of Th17 cell-associated genes (RORC, IL17A, IL17F, and CCR6) was downmodulated in peripheral blood CD4+ T cells in COVID-19 patients." (PMID 37626620, 2023). "In our study, we observed a substantial induction of IL-17A in the control group of COVID-19 patients up to day 8, after which the IL-17A concentration remained significantly elevated compared to the GA/18β treated groups." (PMID 38283346, 2023). "During COVID-19, IL-6 inhibitors were less prescribed (48 (21%) vs. 21 (10%) prescriptions, p = 0.003), while IL-17A inhibitors were more prescribed (39 (17%) vs. 61 (30%) prescriptions, p = 0.001)." (PMID 37623450, 2023). "It was shown that in CD4+ peripheral blood T-lymphocytes of patients with severe COVID-19, there was decreased expression of Th17-associated genes on the example of RORC, IL17A, IL17F and CCR6." (PMID 36674665, 2023).
COVID-19 (continued). "Corroborating to the present study, our group has previously demonstrated a significant positive correlation between IL-17A and SIgA in COVID-19 patients presenting mild/moderate symptoms." (PMID 35686128, 2022). "Our findings revealed that IL-17A levels in severe COVID-19 patients were significantly lower than in mild or moderate COVID-19 patients." (PMID 35958594, 2022). "The percentage and counts of immune-suppressive monocytes (mo-MDSCs) identified as CD14+ HLA-DR− monocytes were higher than normal values in severe COVID-19+ patients, independently from the amount of IL-6, IL-1β, IL-17A, TGF-β, TNF-α and IFN-γ." (PMID 35508575, 2022). "In this study, we screened out a possible link between elevated IL-17A levels and COVID-19 mortality." (PMID 36466533, 2022). "Several groups reported that peripheral Th17 cells and IL-17A in serum are higher in COVID-19 patients than healthy donors." (PMID 34819358, 2022). "This suggests that in more severe COVID-19 patients with higher serum values of IL-17A and/or a higher number of circulating activated TH17, this pathway should be specifically targeted, as we suggested in a previous study." (PMID 35893398, 2022). "Meanwhile, the patient with myopericarditis after COVID-19 vaccination showed a slightly increased level of Th17-type cytokines including IL-17A, IL-17F, and IL-22 compared to healthy controls, but they were lower than those of recently vaccinated controls." (PMID 35251049, 2022). "Studies have also shown that increased levels of IL-17A are a silent amplifier of the COVID-19 immune responses." (PMID 35336918, 2022). "When MAIT cells were stimulated with E. coli, typical upregulation of IFNγ was observed but levels of TNFα and IL-17A were significantly lower in COVID-19-positive individuals compared to healthy controls." (PMID 34050887, 2022). "In intergroup analysis, the COVID-19 groups showed higher salivary levels of IL-10, IL-13, IL-17A, and IFN-α than the control group." (PMID 35686128, 2022). "Herein, we aimed to evaluate the changes in serum IL-6, IL-10, and IL-17A levels and cytometric lymphocyte profiles in 144 COVID-19 patients at admission and after one week, also in relation to steroid treatment before hospitalization." (PMID 35893398, 2022). "Similar results were obtained using molecular biological research methods: the expression of Th17-associated genes (RORC, IL17A, IL17F, and CCR6 decreased in the peripheral blood CD4+ T cells from patients with severe COVID-19." (PMID 35632823, 2022). "Previously, it was shown that CD8+ Tc1 cells able to produce IFNγ, similar to Tc2 (CD8+IL-4+) and Tc17 (CD8+IL-17A+) cells, were lowered in convalescent COVID-19 patients compared to control subjects." (PMID 36146713, 2022). "In contrast to our study, the downregulation of tissue IL-17A/IL-8 and lower neutrophil scores among COVID-19 patients have been reported earlier." (PMID 36298704, 2022). "While IFN-α and IFN-β were undetectable, IL-10, IL-17A and IL-18 were variably detected in COVID-19 BALF, with higher RNA and/or protein levels of IL-6, MCP-1 and IL-33 and lower IL-6 receptor (IL-6R) observed in COVID-19 BALF compared to healthy BALF19,20." (PMID 35589689, 2022). "Both IL-17A and IL-22 can play a significant role in the COVID-19 pathogenesis and be considered therapeutic targets." (PMID 35632823, 2022). "Significantly higher levels of IL-17A have been observed in both mild and severe cases of COVID-19, with highest expression observed in severe cases." (PMID 34050887, 2022). "It has been assumed that cytokines IL-6, IL-17A, and TNF-α are the major players in the cytokine storm and biomarkers for acute respiratory distress syndrome and mortality in patients with COVID-19 and definite risk factors, for example, obesity." (PMID 35684003, 2022).